ANXA1 (annexin A1)
Diseases named in the same sentence as ANXA1 in open-access papers (continued):
Sharing a sentence is not in itself a finding about the gene and the disease.
Cerebral ischemia (16 papers, 2015 to 2025). Restriction of arterial blood supply to the brain associated with insufficient oxygenation to support the metabolic requirements of the tissue. "Our recent study demonstrated that ANXA1 was modified by SUMOylation, and that this modification was greatly weakened after cerebral ischemia, but its effect on neuronal death and the underlying mechanism have not been fully elucidated." (PMID 34158860, 2021). "In this study, we reported and analyzed the effect of cerebral ischemia-induced deSUMOylation of ANXA1 on neuronal apoptosis and the underlying mechanism." (PMID 34158860, 2021). "ANXA1 nuclear translocation is involved in neuronal apoptosis after cerebral ischemia, and extracellular ANXA1 is also associated with regulation of inflammatory responses." (PMID 29844306, 2018). "Meanwhile, administration of the ANXA1 N‐terminal pharmacophore peptide (Ac2‐26) during cerebral ischemia–reperfusion injury promoted the polarization of microglia/macrophages toward the anti‐inflammatory M2 phenotype in the ischemic penumbra." (PMID 40785117, 2025). "ANXA1 also regulates the polarization of microglia/macrophages and protects against cerebral ischemia–reperfusion injury through the FPR2/ALX‐dependent AMPK‐mTOR pathway." (PMID 40785117, 2025). "Overexpression of SUMOylated ANXA1 in microglia/macrophages improves neurological functions in a mouse model of cerebral ischemia." (PMID 38280996, 2024). "ANXA1 is modified by SUMOylation, then SUMOylated ANXA1 facilitates neurological function recovery via increasing M2 microglial polarization in a mouse model of cerebral ischemia." (PMID 38914581, 2024). "We used Tat-NTS peptide to effectively block the nuclear translocation of ANXA1 in microglia, and further observed the effect of Tat-NTS peptide on microglia by promoting the cytoplasmic localization of ANXA1 after focal cerebral ischemia." (PMID 37908731, 2023). "We then conducted experiments to explore the effect of SENP6-mediated deSUMOylation of ANXA1 on neuronal damage after cerebral ischemia." (PMID 34158860, 2021). "As expected, the results also showed that the colocalization of endogenous SENP6 with ANXA1 in the cortex region of mice was significantly increased after cerebral ischemia." (PMID 34158860, 2021). "On the other hand, systemically administration with an inhibitor which could selectively downregulate SENP6 enzyme activity or block its interaction with ANXA1 may provide protective effects against cerebral ischemia-reperfusion injury." (PMID 34158860, 2021). "However, the key enzymes that regulate the SUMOylation status of ANXA1 and its effect on neuronal death after cerebral ischemia remain poorly understood." (PMID 34158860, 2021). "Given the critical role of SUMOylated ANXA1 in microglial polarization and the inflammatory response after cerebral ischemia, SENP6 may also play a role in these processes." (PMID 34158860, 2021). "Importantly, inhibition of SENP6-mediated deSUMOylation of ANXA1 significantly improved neurological function after cerebral ischemia." (PMID 34158860, 2021). "We first confirmed whether ANXA1 could be modified by SUMOylation in neurons after cerebral ischemia." (PMID 34158860, 2021). "Based on our findings, treatments that increase the interaction between S100A11 with ANXA1 may represent a promising therapeutic strategy for cerebral ischemia." (PMID 29844306, 2018). "miR-196a2 and miR-499 could regulate annexin A1 and CRP, which are also the general causes of cerebral ischemia and associated with elevated blood pressure, BMI, insulin resistance, and triglycerides." (PMID 25658319, 2015).
Cerebral ischemia (continued). "Moreover, Tat-NTS—a related peptide—protects against cerebral ischemia/reperfusion injury by enhancing SUMOylation of ANXA1, thereby promoting NBR1-dependent selective autophagic degradation of IKKα, suppressing NF-κB activation, and reducing IL-1β and TNF-α release in microglia." (PMID 41007413, 2025). "Thus, our study positions microglial ANXA1 as a therapeutic target against cerebral ischemia and may achieve a multiplier effect." (PMID 37908731, 2023). "SUMOylation of annexin-A1 (ANXA1), which is involved in the resolution of inflammation, plays a crucial role in modulating microglial polarization after cerebral ischemia." (PMID 38280996, 2024). "Collectively, these results conclusively confirm that cerebral ischemia induces the expression of SENP6 at both the RNA and protein levels and deconjugates SUMO2/3 chains from the ANXA1 protein." (PMID 34158860, 2021). "Finally, having demonstrated the protective effect elicited by AnxA1 postcerebral I/RI coupled with the protection afforded by the protein against cerebral thrombosis (a prerequisite for cerebral ischemia), we determined whether we could further exploit the effects of AnxA1." (PMID 31154815, 2019). "Here, we showed that SENP6 functions as a specific isopeptidase of ANXA1 and that SENP6 could aggravate neuronal damage after cerebral ischemia." (PMID 34158860, 2021). "Interestingly, cerebral ischemia enhanced SENP6 expression at both the RNA and protein levels in neurons and enhanced the binding of SENP6 with ANXA1 in vitro and ex vivo." (PMID 34158860, 2021). "The results suggest that after cerebral ischemia, AnxA1 is a nonredundant factor that promotes an anti-inflammatory/antithrombotic and proresolving environment." (PMID 31154815, 2019). "In addition, overexpression of WT SENP6, but not the SENP6 mutant, reduced the ANXA1 SUMOylation level, facilitated its nuclear and eventually led to neuronal apoptotic death after cerebral ischemia." (PMID 34158860, 2021).
thyroid cancer (16 papers, 2013 to 2025). "Exosomal ANXA1 has been implicated in the malignant transformation of thyroid follicular epithelial cells in thyroid cancer." (PMID 36678567, 2023). "A specific upregulation of annexin A1 in carcinomas of follicular cell origin has been reported previously and suggests that this protein could be a diagnostic and prognostic biomarker for thyroid cancer." (PMID 38203548, 2023). "Conversely, diminished ANXA1 expression has been related to a poor outcome, with reduced survival rates and higher relapse incidence in other types of cancers, e.g., thyroid carcinoma and head and neck squamous cell carcinoma." (PMID 41283264, 2025). "Proteomic analysis identified annexin A1 as a potential biomarker of thyroid cancer malignancy, with its levels increased in malignant samples." (PMID 38203548, 2023). "The correlation between Annexin A1 expression and pathologic differentiation grade has also been reported in several kinds of cancers, such as thyroid cancer, cervical cancer and head neck cancer." (PMID 23786757, 2013). "We found a significant up-regulation of this protein for each type of cancer, supporting the relevance of ANXA1 as ideal candidate biomarker in the diagnosis of thyroid cancer." (PMID 24023790, 2013). "This specific upregulation in carcinomas of follicular cell origin has been reported previously and suggests that annexin A1 could be a prognostic biomarker for thyroid cancer." (PMID 37833989, 2023). "In addition, TCGA THCA (thyroid carcinoma) data extracted from GEPIA website also showed that ANXA1 was increased in PTC samples." (PMID 33531975, 2021).
myocardial infarction (15 papers, 2014 to 2025). Gross necrosis of the myocardium, as a result of interruption of the blood supply to the area, as in coronary thrombosis. "Annexin A1 (ANX1) deficiency results in cardiac necrosis and fibrosis following myocardial infarction and other annexin proteins are up-regulated in a failing heart." (PMID 36728029, 2023). "Relevant for cardiac repair after myocardial infarction (MI), AnxA1 deficiency increased cardiac necrosis, inflammation, hypertrophy and fibrosis following MI and was accompanied by an impaired macrophage phenotype." (PMID 33810523, 2021). "In a 2019 study, the investigators reported significantly increased ANXA1 levels in the blood of patients with myocardial infarction showing disease progression." (PMID 41208642, 2025). "AnxA1 and its derived peptides has both been shown to be cardioprotective in mouse and rat models of myocardial infarction." (PMID 36313572, 2022). "In fact, infusion of recombinant ANXA1 decreases myocardial infarct size and the treatment with Ac2-26 reduces both infarct size, myeloperoxidase (MPO) and IL-1β levels." (PMID 33804219, 2021). "With respect to myocardial infarction, the role of Annexin A1 in neutrophil infiltration and MPO activity were explored in rat." (PMID 34943928, 2021). "Nonetheless, studies focused on therapeutic potential of Annexin A1 have utilized animal models of acute myocardial infarction." (PMID 34943928, 2021). "Myocardial infarction reduced mRNA and protein expressions of Annexin A1, signal transducer and activator of transcription 3 (STAT3) and vascular endothelial growth factor (VEGF) as well as phospho-STAT3 level." (PMID 34943928, 2021). "In addition to increased inflammation, Anxa1-knockout mice exhibited significant increases of fibrosis eight weeks post-myocardial infarction." (PMID 30213070, 2018). "The anti-inflammatory, pro-resolving annexin-A1 protein acts as an endogenous brake against exaggerated cardiac necrosis, inflammation, and fibrosis following myocardial infarction (MI) in vivo." (PMID 31001111, 2019). "It was concluded that Annexin A1 upregulation inhibits neutrophil infiltration and MPO activity likely via the activation of STAT3 signaling pathway in the rat model of myocardial infarction." (PMID 34943928, 2021).
bladder cancer (14 papers, 2013 to 2025). "We confirmed that ANXA1 is associated with higher grade and poor prognosis in bladder cancer, which provides a basis for future development of therapeutic agents." (PMID 35784457, 2022). "Studies in urinary system cancer have shown that renal cancer patients with low expression of ANXA1 have a better prognosis, and Yu’s study showed that high expression of ANXA1 was associated with recurrence of bladder cancer." (PMID 34484309, 2021). "Downregulation of ANXA1 is associated with more rapid cancer recurrence in bladder cancer (6 months vs 12 years)." (PMID 29868478, 2018). "Hence, further research is needed to gain a better understanding of ANXA1 and to assess its potential as a diagnostic or prognostic biomarker and therapeutic target for bladder cancer." (PMID 34991599, 2022). "The results confirmed that a high expression level of ANXA1 was markedly related to poor differentiation, tumor stage and unfavorable prognosis of bladder cancer." (PMID 34991599, 2022). "Only ANXA1 significantly showed overexpression in high grade bladder cancer (p = 0.021, fisher-exact text)." (PMID 35784457, 2022). "GSEA analysis demonstrated that the gene set relevant to bladder cancer was enriched in TCGA samples with high ANXA1 expression." (PMID 34991599, 2022). "Our findings also demonstrated that high expression of ANXA1 is related to the occurrence and development of bladder cancer and affects the prognosis of BC patients." (PMID 35090432, 2022). "The expression of ANXA1–3 was significantly higher in basal-squamous-subtype bladder cancer than in other subtypes and had obvious specificity." (PMID 34484309, 2021). "As it shown, ANXA1 was more strongly stained in high-grade bladder cancer than in low-grade bladder cancer." (PMID 34484309, 2021). "In contrast, it has been shown that expression of ANXA1 was related to inhibition of NFκB in pancreatic and colon cancer cell lines, while in Adriamycin-resistant bladder cancer, ANXA1 has been reported to be downregulated." (PMID 26657294, 2016). "However, decreased ANXA1 expression was also identified in adriamycin-resistant bladder cancer cell lines." (PMID 40361334, 2025). "Meanwhile, high ANXA1 expression predicted the progression and poor prognosis of bladder cancer." (PMID 36741702, 2022). "Taken together, we conclude that ANXA1 could be considered as an independent prognostic factor, and ANXA1- > EGFR may play critical roles in the tumorigenesis in bladder cancer." (PMID 35784457, 2022). "Weighted gene co-expression network analysis (WGCNA), protein–protein interaction (PPI) network mutual analysis, and the Kaplan–Meier survival prognosis analysis were used to identify six key genes associated with the prognosis of bladder cancer: VEGFA, ANXA1, HSP90B1, PSMA7, PRDX6, and PPP1CB." (PMID 36741702, 2022). "Interestingly, we found that bladder cancer with high expression of ANXA1 also showed a squamous pattern, while bladder cancer with high expression of ANXA10 showed a papillary pattern." (PMID 34484309, 2021). "ANXA1 also could promotes the progression and drug resistance in bladder cancer." (PMID 36709279, 2023). "In addition, ANXA1 is significantly overexpressed in bladder cancer than corresponding normal tissues and may be related to the infiltration of immune cells in the TME." (PMID 36741702, 2022). "Moreover, multiple treatments at ultralow (10–20 mg/kg) doses of IF7-10B drug-mediated BNCT significantly suppressed tumor growth in a mouse model of human YTS-1 bladder cancer, with increased Anxa1 expression in tumors and infiltration by CD8-positive lymphocytes." (PMID 33446132, 2021). "According to BC values and the Kaplan–Meier survival curve, six genes related to the occurrence and development of bladder cancer were screened out: VEGFA, ANXA1, HSP90B1, PSMA7, PRDX6, and PPP1CB." (PMID 36741702, 2022).
bladder cancer (continued). "The Kaplan–Meier survival prognosis analysis was performed on the top 100 genes, and 6 genes related to the survival prognosis of bladder cancer were finally screened out: VEGFA, ANXA1, HSP90B1, PSMA7, PRDX6, and PPP1CB." (PMID 36741702, 2022). "We used the TCGA database to analyze the mRNA expression of ANXA1–11 and ANXA13 in bladder cancer tissues and normal tissues." (PMID 34484309, 2021). "We used TCGA data to find that in addition to ANXA1 and ANXA2, other ANXA family proteins (ANXA3, ANXA5, ANXA6, and ANXA9, which have not been studied) are also closely related to the prognosis of bladder cancer." (PMID 34484309, 2021). "The expression of ANXA1, ANXA2, ANXA3, ANXA5, ANXA6, ANXA8, and ANXA13 was closely related to basal-subtype bladder cancer, while the expression of ANXA4, ANXA9, ANXA10, and ANXA11 was closely related to luminal-subtype BC." (PMID 34484309, 2021). "Interestingly, the TM4SF1, ANXA1 and LOX genes have been identified in a fibroblast cluster for good prognosis in bladder cancer and are seen as therapeutic targets for fibrosis." (PMID 40271554, 2025). "ANXA1, ANXA2, ANXA3, ANXA5, ANXA6, ANXA7, and ANXA9 had prognostic value in bladder cancer." (PMID 34484309, 2021). "Five genes in our prognostic model, ANXA1, MAP1B and SPOCD1 have been reported in bladder cancer, however DOK7 and FKBP10 has not been studied in bladder cancer." (PMID 36709279, 2023).
renal carcinoma (14 papers, 2021 to 2025). A carcinoma arising from the epithelium of the renal parenchyma or the renal pelvis. "Additionally, ANXA1 expression was linked to reduced prognosis in gastric, bladder, breast, and renal cancers." (PMID 33959206, 2021). "In renal cell carcinoma, YTHDC1 decreases mRNA stability of the downstream target gene ANXA1 in an m6A-dependent manner and decreases sunitinib sensitivity in renal cancer cells." (PMID 40435202, 2025). "A strong association between ANXA1 expression and the infiltration of myeloid DCs and monocytes in cancers characterized by active immunosurveillance, such as CRC, breast, and renal carcinomas, has been detected." (PMID 41283264, 2025). "RRM2 modulates the anti-tumor effect of sunitinib and PD-1 blockade in renal cancer by stabilizing ANXA1." (PMID 36678567, 2023). "In contrast, we constructed ANXA1, YTHDC1 knockdown alone, or ANXA1 + YTHDC1 coknockdown renal cancer cells." (PMID 35974388, 2022). "We constructed renal cancer cells with stable ANXA1 knockdown induced by transfection with ANXA1-specific shRNAs following puromycin selection." (PMID 35974388, 2022). "Subsequently, we showed that YTHDC1 inhibits the progression of renal cancer cells via downregulation of the ANXA1/MAPK pathways." (PMID 35974388, 2022). "Western blot, quantitative real time PCR (RT‒qPCR), RNA immunoprecipitation PCR (RIP-qPCR), methylated RIP-qPCR (MeRIP-qPCR) and RNA sequencing (RNA-seq) analyses were applied to study the YY1/HDAC2/YTHDC1/ANXA1 axis in renal cancer cells." (PMID 35974388, 2022). "Subsequent in vitro and in vivo cell proliferation studies indicated that knockdown of ANXA1 blocked the effect of YTHDC1 on modulating the sensitivity of renal cancer cells to sunitinib." (PMID 35974388, 2022). "Together, our results demonstrate that YTHDC1 regulates the sensitivity of renal cancer cells to sunitinib through ANXA1." (PMID 35974388, 2022). "We have demonstrated that UBE3A not only degraded ANXA1 in cervical carcinoma cell lines but was also involved in determining the stability of ANXA1 in renal cancer cells." (PMID 34319001, 2021). "We have shown that RRM2 is closely associated with antitumor immune responses and that the RRM2/ANXA1/AKT axis promotes PD‐L1 expression in renal cancer cells." (PMID 34319001, 2021). "With respect to renal cancer, and while the inhibitory effect of Annexin A1 on the proliferation of mesangial cells has been reported, other studies suggest tumorigenesis and malignant potentials." (PMID 34943928, 2021). "Furthermore, Ribonucleotide Reductase M2 (RRM2) stabilizes ANXA1 and modulates the therapeutic efficacy of PD-1 inhibitors and Sunitinib in renal cancer." (PMID 41283264, 2025). "Because YTHDC1 has been reported to regulate the expression level of target genes by influencing their mRNA stability, we speculated whether ANXA1 was the downstream gene of YTHDC1 in renal cancer cells." (PMID 35974388, 2022). "In this study, ANXA1 was proven to be the downstream target gene of YTHDC1 in renal cancer cells." (PMID 35974388, 2022). "Moreover, IHC staining of the tissue microarray indicated that YTHDC1 was negatively correlated with ANXA1 in renal cancer." (PMID 35974388, 2022). "In contrast, overexpression of YTHDC1 decreased ANXA1 expression in renal cancer cells." (PMID 35974388, 2022). "Moreover, we found that RRM2 interacted with and stabilized ANXA1 in renal cancer cells by competing with UBE3A." (PMID 34319001, 2021). "(2021) on renal cancer (RCC) highlights the broader implications of RRM2 and ANXA1 beyond their traditional roles." (PMID 40744683, 2025). "The up‐regulated ANXA1 activates AKT signaling pathway to regulate the sensitivity to sunitinib and PD‐1 blockade in renal cancer cells." (PMID 34319001, 2021).
renal carcinoma (continued). "In conclusion, our results suggest that RRM2 overexpression in renal cancer cells plays a key role in sunitinib resistance in patients with RCC and that RRM2 competes with UBE3A to bind to the C‐terminus of ANXA1, preventing ANXA1 degradation." (PMID 34319001, 2021). "ANXA1, a protein involved in inflammation and apoptosis, has been identified as a mediator of RRM2-induced sunitinib and PD-1 blockade resistance in renal cancer." (PMID 37968699, 2023). "In consistence, we previously demonstrated that RRM2 could stabilize ANXA1 to activate PI3K/AKT signaling and lead to ICIs and sunitinib resistance in renal cancer." (PMID 35081978, 2022). "In addition, from our data it can be noticed that knockdown of RRM2 failed to further decrease AKT S473 phosphorylation in renal cancer cells with co‐knockdown ANXA1." (PMID 34319001, 2021).